FGF23 (fibroblast growth factor 23)
Diseases named in the same sentence as FGF23 in open-access papers (continued):
Sharing a sentence is not in itself a finding about the gene and the disease.
diabetes (continued). "Elevated levels of FGF23 have been associated with the presence and severity of PAD in the population with diabetes mellitus (DM) and preserved kidney function." (PMID 38791495, 2024). "FGF-23 also augments in other conditions often associated with CKD, such as diabetes, anaemia, iron deficiency and inflammation, indicating that its regulation probably is multifactorial." (PMID 38524235, 2024). "Multivariate analysis indicates that SARS-CoV-2 infection predictors included age above 60 years (HR: 2.63 [1.35–5.11], p = 0.004), presence of diabetes (HR: 1.92 [1.05–3.48], p = 0.033) and high plasma FGF23 levels (HR: 1.92 [1.03–3.56], p = 0.039)." (PMID 36828412, 2023). "SGLT2 inhibitors are also thought to promote renal phosphate reabsorption, increase fibroblast growth factor 23 and PTH, and act by decreasing active vitamin D, causing calciuria; however, the effects of diabetes medications on bone health need further study." (PMID 37047250, 2023). "We examined the relationship between parameters related to calcium/phosphate homeostasis, including FGF23 and α-klotho, and subclinical carotid atherosclerosis burden in type 1 diabetes mellitus (T1D) subjects." (PMID 36221075, 2022). "The results of multivariate logistic regression analysis showed that smoking, hypertension, diabetes, alcohol consumption, obesity, HDL-C, FGF23, SAH, Hcy, Homer1 were risk factors for coronary heart disease." (PMID 35546659, 2022). "Various factors, such as phosphate intake and inflammation, have been shown to modify serum FGF23 levels in patients with diabetes." (PMID 36084108, 2022). "Multivariate logistic regression analysis showed that smoking, hypertension, diabetes, alcohol consumption, obesity, HDL-C, FGF23, SAH, Hcy, Homer 1 were independent risk factors for coronary heart disease." (PMID 35546659, 2022). "Multivariate unconditional Logistic regression analysis in this study showed that smoking, hypertension, diabetes, alcohol consumption, obesity, HDL-C, FGF23, SAH, Hcy, and HOMER1 were risk factors for CHD." (PMID 35546659, 2022). "Compelling evidence suggests that the fibroblast growth factor 23 (FGF23) / α-klotho axis is impaired in subjects with diabetes mellitus." (PMID 36221075, 2022). "It is therefore possible that the relation between diabetes and high FGF23 levels is mostly explained by inflammation." (PMID 33716961, 2021). "Chronic inflammation, the hallmark of diabetes, obesity and CKD, contributes to the synthesis of FGF23." (PMID 33673618, 2021). "Further studies are needed to clarify the independence of hypertension and diabetes in elevating systemic levels of FGF-23." (PMID 33767635, 2021). "In this review, we will summarize the literature on potential factors driving FGF23 deregulation in diabetes." (PMID 32857288, 2020). "Overall, future studies should evaluate the value of antidiabetic medication in reducing FGF23, to further clarify the role of FGF23 in patients with diabetes." (PMID 32857288, 2020). "After excluding participants with diabetes mellitus and quality control, association of single nucleotide polymorphisms (SNPs) with log-transformed FGF21 and FGF23 serum concentrations adjusted for age, sex and principal components of ancestry were analyzed." (PMID 32884031, 2020). "Our results support a relationship between FGF-23 and imaging markers of diabetic cardiomyopathy, and FGF-23 has previously been proposed as a potential predictor of cardiovascular disease in patients with diabetes." (PMID 32998751, 2020). "Future studies are clearly needed to further advance this field and better understand the deregulations in phosphate metabolism, including FGF23, in patients with diabetes." (PMID 32857288, 2020). "Patients in the top quartile of FGF23, compared to the bottom quartile, were more likely to be female, have a history of diabetes, prior CVD or a history of atrial fibrillation." (PMID 30830941, 2019).
diabetes (continued). "Serum FGF23 levels were independently and positively correlated with the presence of lowerextremity atherosclerotic disease among Chinese patients with type 2 diabetes mellitus." (PMID 30424752, 2018). "We consider that diabetes decreases the number of nephrons, even when eGFR is preserved and impairs renal sensitivity to FGF23." (PMID 30245879, 2018). "This study is the first to show that resistin and FGF23 are significantly associated, even on multiple regression analysis including renal function, PTH, vitamin D status, and markers of diabetes." (PMID 30228288, 2018). "For use of serum FGF23 levels in the clinical evaluation of first-degree relatives of patients with diabetes, the influence of a first-degree FHD should be considered to avoid overestimation of the CVD risk in this population." (PMID 27698482, 2016). "Consistently, the present study found that first-degree relatives of patients with diabetes exhibited higher levels of serum FGF23 at an equivalent degree of subclinical atherosclerosis as assessed by the C-IMT." (PMID 27698482, 2016). "The goal of the present study was to explore alteration in serum FGF23 levels and to assess its value for identifying subclinical atherosclerosis in normoglycemic individuals with a first-degree family history of diabetes (FHD)." (PMID 27698482, 2016). "A community-based study proposed that an elevated FGF23 concentration is a subclinical marker of metabolic perturbations (diabetes, dyslipidemia, and obesity) in individuals with normal kidney function." (PMID 27698482, 2016). "Only in diabetes subjects did they observe a significant increase in serum FGF23 levels after clamp, which was correlated with the increase in insulin levels." (PMID 27698482, 2016). "In the multivariate analysis including sex, body mass index (BMI), age, PTH, eGFR, FePi, serum phosphate, serum calcium, total cholesterol, systolic blood pressure, proteinuria, diabetes and smoking, only eGFR and smoking were independent predictors of FGF23." (PMID 25700931, 2015). "This trend remained significant even after adjusting for age, gender, diabetes mellitus, sPi, sAlb, Hb, 1,25(OH)2D, and FGF23 (HR 6.33, 95% CI 1.70–25.44; p = 0.0065)." (PMID 26604925, 2015). "The patients in the highest FGF23 tertile were more likely to be older, female or have preexisting diabetes." (PMID 25902817, 2015). "Multivariate analysis showed that diabetes mellitus, smoking, and log FGF23 remained as independent determinants for CAAC." (PMID 23339433, 2013). "The proportions of participants who had used cholesterol-lowering agents, anti-diabetes drugs, and antihypertensive drugs were highest in the highest quartile and lowest in the lowest quartile of serum FGF23 (all P<0.001)." (PMID 24015259, 2013). "We also performed a stepwise linear regression model on the FGF23 adjusted for age, gender, race, smoking, hypertension, diabetes, body mass index, 25(OH)D, total calcium, phosphorus, log PTH, urea, and creatinine clearance." (PMID 22590632, 2012). "Phosphorus remained a significant risk factor for CAC even after adjustment for multiple variables such as age, gender, diabetes, hypertension, FGF23 level, and PTH concentration." (PMID 22590632, 2012). "OP and DPN shared long diabetes duration, high FGF23, and low Apelin-13." (PMID 42200082, 2026). "FGF-2, FGF-19, FGF-22, and FGF-23 likely significantly impact diabetes and its complications." (PMID 40943671, 2025). "Epidemiological data indicate that elevated FGF23 levels are associated with an increased risk of type 2 diabetes and posttransplant diabetes, independent of traditional risk factors." (PMID 40237064, 2025). "In light of these limitations, further large-scale studies with more homogeneous cohorts, incorporating medication tracking, and longitudinal follow-up are necessary to validate the current results and clarify the mechanistic and prognostic roles of FGF-2, FGF-19, FGF-22, and FGF-23 in diabetes." (PMID 40943671, 2025).
diabetes (continued). "These initial observations should stimulate further research addressing the relationships of deregulated FGF23 and other factors involved in mineral metabolism with the risks of developing diabetes and cardiovascular disease in populations with normal kidney function." (PMID 40237064, 2025). "The changes seen for DKK1, cathepsin A, cathepsin S, cathepsin Z, and FGF23 that potentially favor a bone resorptive state may contribute to the resorptive effects of RANKL in diabetes." (PMID 41373586, 2025). "No therapies specifically target FGF23 to lower diabetes risk, but fibroblast growth factor receptor 4 (FGFR4) inhibitors show promise." (PMID 40237064, 2025). "Given the clinical relevance of glycemic control, Spearman’s rank correlation analysis was conducted to assess the relationship between glycated hemoglobin (HbA1c) levels and concentrations of selected fibroblast growth factors (FGF-2, FGF-19, FGF-22, and FGF-23) in patients with diabetes (n = 73)." (PMID 40943671, 2025). "Subgroup analyses were conducted to examine the association between sKlotho concentration and CVD events across different patient characteristics, including age, history of CVD, diabetes mellitus, phosphorus levels, iPTH, FGF23, cinacalcet use, and vitamin D analog use." (PMID 41141519, 2025). "Worst kidney function and diabetes were also found to be contributing to FGF23 levels." (PMID 38791495, 2024). "This work aimed to study whether fibroblast growth factor 23 (FGF23) is predictive for incident posttransplant diabetes mellitus (PTDM) in kidney transplant recipients (KTRs)." (PMID 38577264, 2024). "In the literature, there are a few hypotheses explaining the relationship between elevated FGF23 level and diabetes mellitus." (PMID 37371618, 2023). "There were no important differences in age, sex, lifestyle factors, anthropometric measurements, blood pressure, prevalence of diabetes mellitus, glycated hemoglobin levels, eGFR, and markers of calcium/phosphate homeostasis across fifths of the FGF-23 genetic score." (PMID 36719157, 2023). "Concerning DKD, a case control study of patients enrolled in the Action to Control Cardiovascular Risk in Diabetes (ACCORD) Trial demonstrated that baseline serum FGF23 levels did not predict the CKD incidence in 590 T2D patients." (PMID 36084108, 2022). "Finally, the association between a high FGF-23 level and a high risk of RKFD was consistent across subgroups of age, sex, CVD, hypertension, diabetes, metabolic syndrome, and gout." (PMID 36671416, 2022). "The endocrine subfamily of FGFs, consisting of FGF19, FGF21, and FGF23, might have beneficial effects in the treatment of diabetes mellitus (DM) and/or obesity." (PMID 36699319, 2022). "Apart from FGF-23, some traditional prognostic factors could also predict MACCE risk in ULMCAD patients receiving CABG, including age ≥65 years, diabetes, previous stroke, LVEF <50%, and higher disease extent, which was in line with a previous study." (PMID 36132198, 2022). "This early tubular dysfunction could, at least, partly contribute to the higher blood FGF23 levels in patients with diabetes." (PMID 35216490, 2022). "Fibroblast growth factor 23 (FGF23), a potential biomarker for kidney function, is related to cardiovascular disease (CVD) and diabetes, although it is unclear whether the relation is causal." (PMID 34367258, 2021). "Together these results indicate that insulin is an inhibitor of FGF23, at least partially independent of the inflammation associated with diabetes." (PMID 33716961, 2021). "Patients with diabetes had increased FGF23 levels and presented an earlier onset of FGF23 excess." (PMID 34208131, 2021). "Our results suggested that 1,25D could promote osteogenesis though down‐regulating FOXO1/FGF23 in diabetes." (PMID 33609082, 2021). "Since FGF23 target tubular epithelial cells to promote phosphaturia, early tubular dysfunction could at least partly contribute to higher FGF23 levels in diabetes [14••]." (PMID 32857288, 2020).
diabetes (continued). "Diabetes-related factors may influence plasma FGF23 levels, and a higher FGF23 levels seem to contribute to a higher cardiovascular and mortality risk in patients with type 2 diabetes." (PMID 32857288, 2020). "Third, decreased bone formation rates as observed in patients with diabetes could be a stimulus for FGF23 secretion." (PMID 32857288, 2020). "They included the age, dialysis vintage, average ultrafiltration, Log (CACS + 1), warfarin use, serum potassium, hsCRP, phosphate, uric acid, iPTH, Mg < 2.4 mg/dl, serum albumin, gender (male), presence of diabetes mellitus, urine volume ≥ 100 ml/day, and Log FGF23 at baseline." (PMID 30977017, 2019). "We therefore aimed to identify the effects of FGF23 independent of kidney disease by studying a prospective cohort with normal kidney function, but with CV risk factors that included diabetes, hypertension, and hyperlipidemia." (PMID 30192823, 2018). "FGF-23 may also play a role in some metabolic processes, such as insulin resistance (IR), and may also be a marker of diabetes progression or may increase with diabetes-related complications." (PMID 30462803, 2018). "Due to multiple homeostatic imbalances occurring with hyperglycemia in diabetes, endothelial dysfunction might be induced by multifactorial etiologies, of which altered FGF23 might be one." (PMID 28619026, 2017). "Based on these results, the heritability of diabetes could be responsible for the elevation in serum FGF23 levels, even when blood glucose levels are in the normal range." (PMID 27698482, 2016). "The abnormality of insulin action may be an explanatory factor for the alteration in serum FGF23 levels in the first-degree relatives of patients with diabetes." (PMID 27698482, 2016). "There is only a previous study evaluating FGF-23 in diabetes." (PMID 26462160, 2015). "Interfering pharmacologically with the delicate balance of FGF23 and phosphorus in diabetes may have implications in clinics." (PMID 23967103, 2013). "The results of the study demonstrate that vascular calcification is closely associated with serum osteoprotegerin levels in patients with diabetes, but is not linked to other bone-related humoral factors including osteocalcin, FGF23, and 25-hydroxyvitamin D3." (PMID 23302066, 2013). "In patients with CKD FGF23 is significantly associated with proteinuria and smoking, along with other, already established associations, like eGFR (inverse relation), plasma phosphate level, PTH, history of cardiovascular disease and diabetes mellitus." (PMID 22530966, 2012). "In addition, inflammation is an important trigger of both FGF23 production and new-onset diabetes, and as such a pro-inflammatory environment could (partly) explain higher FGF23 levels in individuals prone to develop diabetes." (PMID 40237064, 2025). "Diabetes mellitus is characterized by a combination of various somatic factors and factors that affect renal function such as advanced glycosylated end-product, pro-renin, cytokine, and nephrin expression, changes in the renin–angiotensin–aldosterone system, and FGF-23 degradation." (PMID 40685514, 2025). "In line with the preceding lines of evidence that connect higher FGF23 levels with deregulated glucose metabolism and insulin resistance, several studies have demonstrated that individuals without diabetes who have a higher FGF23 level are at increased risk of developing type 2 diabetes." (PMID 40237064, 2025). "Potential confounding factors like diabetes mellitus, CKD, vitamin D and calcium metabolism or medications varied among the study populations, potentially decreasing the ability to form independent conclusions in predicting the association of FGF-23 with plaque instability." (PMID 40137447, 2025). "This may indicate a potential role for FGF-23 as a marker of metabolic dysregulation in diabetes." (PMID 40943671, 2025).
diabetes (continued). "Finally, multivariate analysis indicates that the predictors of severe COVID-19 also included age above 60 years (HR: 2.65 [1.22–5.77], p = 0.014), presence of diabetes (HR: 2.52 [1.25–5.06], p = 0.009) and high plasma FGF23 levels (HR: 2.12 [1.04–4.28], p = 0.036)." (PMID 36828412, 2023). "Thus, the increase in the FGF23 levels generated by SGLT2i is noticeable, as it may result in adverse diabetes outcomes including fracture and cardiovascular events." (PMID 35966090, 2022). "However, the underlying mechanism between 1,25D and FGF23 in diabetes‐induced bone metabolism disorders has not yet been elucidated." (PMID 33609082, 2021). "Although these associations were not statistically significant in multivariable adjusted models, the results suggested for the first time that hyperinsulinemia and IR might be contributing factors to the increase in circulating FGF23 levels in the diabetes population." (PMID 34208131, 2021). "In conclusion, high plasma levels of FGF-23 are associated with certain demographics, such as age and sex; with cardiovascular diseases like LVH, HF and AF; with clinical disturbances such as low eGFR, high phosphate and NT-pro-BNP; and with comorbidities like diabetes and hypertension." (PMID 33767635, 2021). "Thus, although the initial discovery linking G3P with FGF23 production was in acute kidney injury, this concept also provides an hypothetical link between dysregulated G3P metabolism and FGF23 levels in patients with diabetes." (PMID 32857288, 2020). "Several factors may contribute to deregulated FGF23 in patients with diabetes." (PMID 32857288, 2020). "The elevation in circulating FGF23 levels, which was also observed in diabetic animal models, might aggravate the existing endothelial dysfunction and stimulate vascular calcification, ultimately leading to atherosclerosis in diabetes." (PMID 28619026, 2017). "Given that diabetes is an established risk factor for lower extremity atherosclerotic disease (LEAD), the goal of the present study was to explore the relationship between serum FGF23 levels and LEAD, as well as the related factors, in Chinese patients with type 2 diabetes mellitus (T2DM)." (PMID 28619026, 2017). "DM, diabetes mellitus; eGFR, estimated glomerular filtration rate; FGF23, fibroblast growth factor 23; U-P, 24-h urinary excretion of phosphate; OR, odds ratio." (PMID 27504998, 2016). "If not, the use of serum FGF23 as a biomarker in first-degree relatives of patients with diabetes may result in overestimation of the CVD risk." (PMID 27698482, 2016). "In our study, patients with diabetes and coexisting mood disorders exhibited higher levels of FGF-2 and FGF-23." (PMID 40943671, 2025). "Finally, FGF23 may not be a cause of incident diabetes, but rather an expression of deregulated mineral metabolism in early diabetes." (PMID 40237064, 2025). "Additionally, the study did not evaluate confounding factors such as hypertension or diabetes, which may influence serum FGF23 levels and its association with CI and VBI." (PMID 39096857, 2024). "However, with the increasing prevalence of CKD-inducing pathologies such as diabetes mellitus or hypertension in today’s society that may persistently trigger FGF23 production, the cost of some FGF23-related functions has exceeded their benefit, thus culminating in disease." (PMID 34050126, 2021). "Compared with survivors, participants who died had older age, more smoking habits, more comorbidities (diabetes, CAD, stroke, and cancer), higher FGF23 levels, and lower eGFR levels." (PMID 32581247, 2020). "The results of univariate Cox regression analysis suggest that age, incidence of diabetes, dialysis vintage, ALB, and median sKlotho and FGF23 levels significantly affected total adverse events." (PMID 33299496, 2020).